ENSG00000238485
Synonyms: LOC124905269
Gene: Small nucleolar RNA gene on chromosome X (139,702,287 to 139,702,390, reverse strand). Ensembl gene ENSG00000238485.
Gene Ontology:
Biological process: RNA processing
Cellular component: nucleolus
Homologues: Paralogues in human: SNORD13 (83% identical), SNORD13P1 (83% identical), SNORD13P3 (82% identical), SNORD13D (81% identical), SNORD13E (81% identical).